EPC2 (enhancer of polycomb 2)
Description:
May play a role in transcription or DNA repair.
Synonyms: DKFZP566F2124; EPC-LIKE
Tractability: PROTAC: UniProt records ubiquitination sites on it; ubiquitination databases record sites on it; its protein half-life has been measured.
Gene: Protein-coding gene on chromosome 2 (148,644,440 to 148,788,609, forward strand). Ensembl gene ENSG00000135999.
Subcellular location: Nucleus
Subcellular location (Human Protein Atlas): Nuclear speckles
Gene Ontology:
Molecular function: protein-macromolecule adaptor activity
Biological process: positive regulation of double-strand break repair via homologous recombination; regulation of cell cycle; chromatin organization; positive regulation of DNA-templated transcription; regulation of apoptotic process; regulation of double-strand break repair; regulation of transcription by RNA polymerase II
Cellular component: NuA4 histone acetyltransferase complex; nucleosome; piccolo histone acetyltransferase complex; nucleus
Genetic constraint (gnomAD): Loss-of-function variants: 8 observed, 71.21 expected, observed/expected ratio (o/e) 0.11, 90% interval 0.065 to 0.2. The upper end of that interval is the gene's LOEUF score, 0.2, which puts it in group 1 of 6, group 1 being the genes least tolerant of losing a copy. Missense variants: 676 observed, 878.75 expected, observed/expected ratio (o/e) 0.77, 90% interval 0.72 to 0.82. Synonymous variants: 310 observed, 304.08 expected, observed/expected ratio (o/e) 1.02, 90% interval 0.93 to 1.12.
Homologues: Orthologues: chimpanzee EPC2 (99% identical), pig EPC2 (99% identical), dog EPC2 (99% identical), guinea pig EPC2 (98% identical), mouse Epc2 (97% identical), macaque EPC2 (97% identical), rat Epc2 (97% identical), rat AC142154.1 (96% identical), rabbit EPC2 (93% identical), tropical clawed frog epc2 (86% identical), zebrafish epc2 (59% identical), Drosophila melanogaster E(Pc) (36% identical), and 1 more. Paralogues in human: EPC1 (55% identical).
Diseases named in the same sentence as EPC2 in open-access papers:
EPC2 is named in the same sentence as 8 diseases in open-access papers, as found by Europe PMC text mining. Sharing a sentence is not in itself a finding about the gene and the disease. The quoted sentences say what the papers report.
endometrial stromal sarcoma (2 papers, 2018 to 2021). "Intriguingly, besides AML-related ZM fusion, aberrant chromosomal rearrangements detected in endometrial stromal sarcoma patients recurrently target components of NuA4/TIP60 complex such as EP400, EPC1, EPC2, MEAF6 and MBTD146–50." (PMID 33594072, 2021).
acute myeloid leukemia (1 paper, 2024). Acute myeloid leukemia (AML) is a group of neoplasms arising from precursor cells committed to the myeloid cell-line differentiation. "EPC1 and EPC2 are also related to acute myeloid leukemia (AML), which can directly or indirectly suppress the accumulation of MYC and apoptosis of AML cells, thereby maintaining oncogenic potential." (PMID 38439957, 2024).
osteosarcoma (1 paper, 2024). A usually aggressive malignant bone-forming mesenchymal neoplasm, predominantly affecting adolescents and young adults. "EPC1 and EPC2, the components of the EP400 and Tip60-EP400 complexes, have been reported to activate gene expression by stimulating H3.3 deposition into promoters and enhancers in U2OS human osteosarcoma cells." (PMID 38439957, 2024).
EPC2 also shares sentences with these, for which no sentence is quoted: tumor (2 papers); cancer (1); medulloblastoma (1); melanoma (1); neuroblastoma (1).